ENSG00000277583
Gene: Miscellaneous RNA gene on chromosome 7 (116,953,214 to 116,953,324, forward strand). Ensembl gene ENSG00000277583.
Homologues: Orthologues: mouse Gm55212 (68% identical).